CD80 (CD80 molecule)
Diseases named in the same sentence as CD80 in open-access papers (continued):
Sharing a sentence is not in itself a finding about the gene and the disease.
cancer (continued). "Methylation of CpGs annotated to the promoters of LAG3, CTLA4, CD86, CD80, and HAVCR2 also decreases with age pan-cancer." (PMID 34433020, 2021). "Phagocytosis was proven, using 5-chloromethylfluorescein diacetate (CMFDA), to pre-label cancer cells and, more importantly, DC maturation was documented by the increased expression of co-stimulatory molecules CD40, CD80 and CD86." (PMID 32120810, 2020). "IFN-α/GM-CSF stimulation leads to the increased expression of HLA-DR, CD11c, CD83, B7 costimulatory molecules CD80 and CD86, including on DCs of cancer patients, and such DCs are able to efficiently present an antigen to CD4+ and CD8+ T-cells." (PMID 32582698, 2020). "The basal expression of the CD80, CD86 and HLA-DR molecules in the three APC populations was largely comparable between the healthy subjects and the cancer patients, before and after chemotherapy." (PMID 31973714, 2020). "Autologous cancer vaccines were able to, on average, stimulate an up-regulation of MHC-II and CD80 by 48-fold as compared to media only (MHC-II + CD80 + cells: 12.19 ± 3.70% vs. 0.25 ± 0.06%; p < 0.001)." (PMID 33208160, 2020). "The expression of CD80, CD86 and HLA-DR molecules was evaluated in CD14−CD123+ plasmacytoid dendritic cells (pDCs) from cancer patients, before and after chemotherapy, upon ex vivo treatment with the adjuvants." (PMID 31973714, 2020). "Lastly, as compared to MIM-SIS adjuvant only, autologous cancer vaccines increased the expression of MHC-II and CD80 by 9-fold (MHC-II + CD80 + cells: 12.45 ± 3.53% vs. 1.33 ± 0.36%; p < 0.001)." (PMID 33208160, 2020). "The total number of activated CD103+ CD86+ and of CD103+ CD80+ cell subsets rose 10% and 12% by FACS, respectively, in the immune cells co-cultured with Poly(I:C)/INFα-treated-H460 cancer cells versus untreated H460 cells." (PMID 32093313, 2020). "CTLA-4 competes with CD28, a costimulatory receptor, for ligands B7-1 (CD80) and B7-2 (CD86) on cancer cells or antigen-presenting cells." (PMID 32117298, 2020). "It is only when autologous cancer cells and MIM-SIS adjuvant are combined that there is a 53.7% increase in dual signaling of MHC-II and CD80 on canine cells, and thus a more robust potential for immune activation." (PMID 33208160, 2020). "Recent studies have suggested that immune checkpoints play an important role in the immune escape of cancer, so we further analysed the relationship between the 4 subtypes and 8 immune checkpoint genes (PDCD1, CD274, PDCD1LG2, CTLA4, CD86, CD80 and CD267)." (PMID 31995855, 2020). "The PD-1/PD-L1 immune checkpoint blockage in cancer therapy, the interfering CD28 and CD80/CD86 binding with CTLA-4-Ig in the treatment of rheumatoid arthritis and using anti-CTLA-4 monoclonal antibody (mAb) for cancer treatment are the best examples." (PMID 31120992, 2019). "We therefore evaluated the expression of maturation markers, namely MHC-II, CD80, and CD86, upon exposure to PDT-killed cancer cells." (PMID 31508370, 2019). "In co-stimulators, we demonstrated that the CD80 and CD28 expression was highly correlated with PD-1 in some of cancer types." (PMID 30607140, 2018). "Chromogenic double staining with CD80 and CD68 in primary OSCC samples revealed centered distribution of M1-like macrophages in CD68+ clusters among the cancer nests." (PMID 29986759, 2018). "We studied the expression of CD80, CD86 and MHC-II on the surface of B lymphocytes from cancer patients, compared to cells from healthy donors." (PMID 29975708, 2018). "The percentage of CD80+CD86+ cells, however, increased by a factor of 2.64 fold in cancer patients upon stimulation, while in healthy subjects this increase was 3.84 fold." (PMID 29975708, 2018). "Two antagonistic anti-CTLA-4 mAbs, ipilimumab (IgG1 isotype) and tremelimumab (IgG2 isotype), that block interactions between CTLA-4 and its coreceptors CD80 and CD86 have been clinically approved for advanced stage cancers." (PMID 28515726, 2017).
cancer (continued). "We have also reported that the expression of costimulatory ligands CD80 and 4-1BBL on murine CD4 T-cells prolonged their longevity in vitro and in vivo, indicating their potential for use as alternative APCs for cancer immunotherapy." (PMID 27323820, 2016). "For example, intra-tumoral DCs obtained from cancer patients or cancer-bearing experimental animals display lower expression of MHC class I and II as well as CD80 and CD86 molecules." (PMID 24782988, 2014). "The agonistic CD28 ligands B7.1 (CD80) and B7.2 (CD86), physiologically expressed on APCs, are missing on most cancer cells with the consequence that the CD3ζ CAR upon binding to cancer cells does not provide the costimulation required for full activation." (PMID 24273543, 2013). "For the same activation protocol used in this work we have repeatedly shown a strong upregulation of CD80, CD86 and HLA-DR both for B cells of healthy donors and of cancer patients." (PMID 22592077, 2012). "In fact, LPS-induced upregulation of CD80, CD86 and CD83, and the expression of IL-10 were similar in cancer patients and healthy controls." (PMID 14562018, 2003). "Notably, abatacept (a CTLA-4-Ig fusion protein that binds CD80/CD86) has demonstrated the ability to modulate T-cell activation and has shown antitumor activity in immunologically active cancers." (PMID 40445003, 2025). "Furthermore, co-culturing immature dendritic cells with dying cancer cells targeted by EGFR and TF NIR-PIT agents mediated enhanced dendritic cell maturation, as indicated by increased expression of CD80, CD86, CD40, and HLADR." (PMID 41362788, 2025). "Treg cells have the ability to limit the function of antigen-presenting cells by CTLA-4-dependent downregulation of CD80 and CD86, thereby playing a detrimental role in suppressing cancer progression by evading immune surveillance and suppressing the antitumor immune response." (PMID 38238581, 2024). "The correlation between a higher percentage of Vim+, CD80+, and CD155+ cancer cells and a higher risk of progression/relapse was not significant in all cohorts, but a trend was observed that should be validated with a larger number of patient samples." (PMID 38914547, 2024). "In contrast, expression levels of TGF-β, CD39, CD73, PD-1, OX40 and CD80 were comparable in sEV from cancer and non-malignant cells." (PMID 37542121, 2023). "In addition, the expression of CD80 and CD86 was further increased when the macrophages were stimulated with LPS and IFN-γ before coculture with HER2-positive cancer cells in both the GFP-M and CAR-M groups." (PMID 36978075, 2023). "Therefore, the interaction of CTLA-4 and CD80/CD86 inhibits the T cell activation signal, resulting in the suspension of the cancer-immunity cycle." (PMID 36980950, 2023). "Moreover, Hyp PDT induced phagocytosis of cancer cells by DCs and induced upregulation of maturation markers CD80, CD86 and CD40 to a larger extent than DCs co-cultured with F/T treated cancer cells." (PMID 36839652, 2023). "Type 1 conventional CD103+ migrating DCs are antigen-presenting cells (APCs) that elucidate CTLs before cancer cell detection via three different mechanisms: cancer antigen adhered to MHC-I, co-stimulatory molecules (CD80/86 and CD28/152), and pro-inflammatory cytokines (IL-12 and TNF-α)." (PMID 36560420, 2022). "It was known that CD80 is expressed in TNBC cell lines, which could interact with PD-L1 in cis, so the density of CD80 on cancer cells was also estimated by that on mature dendritic cells." (PMID 35856032, 2022). "The binding between CD80 on antigen-presenting cells (APCs) and CD28 on naive T cells results in T cell activation in the lymph nodes, which elevates the immune response and kills cancer cells." (PMID 36142412, 2022).
cancer (continued). "As the target of the first cancer immunotherapeutic agent (ipilimumab) in clinic, CTLA-4 outcompetes CD28 in binding to CD80/CD86 on APCs, modulating the fine-tuning of TCR signaling and, therefore, preventing autoimmune diseases caused by hyperactivation of T lymphocytes." (PMID 34064396, 2021). "The CTLA-4 co-inhibitory receptor is constitutively expressed on T cells and competes with CD28 co-stimulatory receptor for binding to their cognate ligands CD80 (B7.1) and CD86 (B7.2) on cancer cells, for which it has a greater affinity, thereby effectively inhibiting CTL activation." (PMID 33808294, 2021). "Ultimately, HDIs may regulate cancer cell immunogenicity by upregulating molecules participating in T-cell and natural killer cell activation, such as MHC class I and II, CD80/CD86, and MHC class I chain-related molecules (MICA/MICB)." (PMID 34769131, 2021). "The absence or low-level expression of CD80 and CD86 in cancers could be one of the mechanisms in which cancers escape immunosurveillance." (PMID 33092083, 2020). "Notably, autologous cancer vaccines (n = 13) were able to, on average, stimulate an up-regulation of MHC-II and CD80 by 48-fold as compared to media only (MHC-II + CD80 + cells: 12.19 ± 3.70% vs. 0.25 ± 0.06%; p < 0.001)." (PMID 33208160, 2020). "The RNAdjuvant® induced the strongest activation of CD80 expression in monocytes from cancer patients, pre and post-chemotherapy, compared to negative control and other adjuvants." (PMID 31973714, 2020). "MOF-gated MS most efficiently enhances cancer antigen presentation, upregulates the expression of costimulatory molecules (CD40 and CD80), and promotes chemokine receptor CCR7 expression, which implies their great potential in cancer vaccines, compared with MS or MOF." (PMID 32737343, 2020). "Consistently, the polarized THP-1 cells revealed the induced amounts of M1 marker (iNOS and CD80) and the reduced amounts of M2 marker (CD163 and Arginase-1) while reacting with the cancer cells those were pretreated with Oligo-Fucoidan or in combination with cisplatin." (PMID 32059469, 2020). "Moreover, CD80 (B7-1), B7-2 (CD86)/CTLA-4, and B7-H1 (PD-L1)/PD-1 have been identified as promising targets and their inhibitors have achieved great success in cancer immunotherapy." (PMID 30609841, 2019). "mDCs manufactured using GM-CSF and IL-4 primed with OK-432 for clinical use expressed the HLA−ABC+DR+CD40+CD80+CD86+CD197+ phenotype, harboring bioactive functions that could be useful in providing personalized vaccines for cancer immunotherapy." (PMID 31546936, 2019). "Considering the different affinity of CD86 and CD80 for CD28 and CTLA-4, respectively, and the constitutive expression of CTLA-4 in Treg cells, cancer cells could induce antigen tolerance towards themselves by modulating Treg cell functions." (PMID 30123257, 2018). "To study this hypothesis, we used FACS analysis to quantify the expression of the three target receptors of CTLA4-FasL, namely CD80 (B7.1), CD86 (B7.2) and CD95 (Fas), on the different human cancer cell lines." (PMID 25227919, 2014). "For example, administration of B7-1 (CD80) and B7-2 (CD86), proteins that provide the crucial second signal required for T-cell activation, has been shown to increase CTL activity in cancer and HIV, respectively." (PMID 24204366, 2013). "Importantly, expression of Cd80 was not significantly affected by either cancer cell medium or infection, and B7-H4 (Vtcn1) was very low in any of the experimental groups." (PMID 40547518, 2025). "This targeting mechanism of ExoDS may be attributed to a variety of membrane receptors like integrin α and β chains (αMβ2), ICAM-1, MFG-E8, TNF, FasL, CD86, CD80, CD40, CD83, MHC-I, MHC-II, NKG2D, IL-15Rα, CD21, CD11c, and CCR7, which help mDC-derived exosomes identify cancer cells." (PMID 38903193, 2024).
cancer (continued). "While none of the compounds affected CD80 expression, several of them, including ureas 2 and 11 and carbamate 14, were found to significantly reduce CD11b expression, which is a promising target for immune modulation in anti-cancer therapies." (PMID 37239929, 2023). "It is known that HLA-ABC is crucial for proper presentation of specific antigens on the cancer cell surface for recognition by cytotoxic CD8 T cells, and that full activation of CD8 T cells requires both expression of HLA-ABC and expression of the T cell costimulatory molecule CD80 or CD86." (PMID 35954154, 2022). "We found that LLC cancers treated with I + C exhibited a significant increase in the local presence of activated DCs expressing CD11c and CD80 but no change in the local presence of classic macrophages (M1), alternative macrophages (M2), activated NK cells, activated NKT cells, or MDSCs." (PMID 36057637, 2022). "One important highlight is the observation that HDAC inhibition could improve cancer cells’ immune response via the regulation of the expressions of tumor antigens, including CD40, CD80, CD86, MHC, ICAM-1 and MICA/B, which drive the elimination of cancer cell proliferation through the immune system." (PMID 35158821, 2022). "This cytokine is frequently upregulated in cancers and has been shown to directly affect the function of APCs by inhibiting the expression of major histocompatibility complex (MHC) class II and costimulatory molecules CD80/B7-1 and CD86/B7.2, which in turn induces immune suppression or tolerance." (PMID 34079545, 2021). "CD80 expressing cancer cells have been identified in human skin SCC and pre-neoplastic colon lesions, and our analysis of human cancer cell line transcriptomics data further suggests that cancer cell CD80 expression is present in a broad range of solid epithelial cancers." (PMID 31959281, 2020). "CD80-Fc provided the most robust antigen-specific immune response to STEAP1 and may be considered a potential universal adjuvant as it significantly boosted several additional cancer vaccines of interest." (PMID 32161596, 2020). "However, the prevalence of CD80 expression in human cancer cells has not been extensively characterized." (PMID 31959281, 2020). "The results showed that the basal expression of the CD80, CD86 and HLA-DR molecules in monocytes, myeloid dendritic cells (mDCs) and plasmacytoid dendritic cells (pDCs) was largely comparable between healthy subjects and cancer patients, before and after the chemotherapy." (PMID 31973714, 2020). "However, combination therapy using a FAK inhibitor and agonistic antibodies against OX-40 or 4-IBB, receptors important for T cell activation, was able to overcome CD80-negative cancer cell insensitivity to FAK inhibition." (PMID 32514188, 2020). "Importantly, the ligands of CTLA-4 B7-1 (CD80) and B7-2 (CD86) are expressed on antigen presenting cells (APC) but not on cancer cells, whereas the ligands of PD-1, PD-L1 and PD-L2, are expressed on APC and on cancer cells." (PMID 27510264, 2016). "Consistently, immunostaining using CD80, a marker specific for M1, and CD209, a marker specific for M2a, showed that the various macrophages retained the expression of their respective markers after 36 h, even within the 3D collagen matrix in the presence of carcinoma aggregates and HUVECs." (PMID 26231039, 2015). "In cancer patients, inflammatory changes indicate that IDO may be induced by soluble factors including IFNγ, TNF-α, IL-1β, soluble CD40 ligand (sCD40L) and CTLA-4 ligation to CD80/CD86 expressed by DC." (PMID 24147117, 2013). "Importantly, cancer cells can deliver Signal 1 to tumor-infiltrating lymphocytes (TILs) through MHC presentation of neoantigenic peptides yet are unable to deliver costimulatory Signal 2 because, like most epithelial cells, they typically lack expression of CD80 or CD86." (PMID 39301613, 2025).
cancer (continued). "The expressions of MHC molecule H-2Kb and co-stimulator factors (CD80 and CD86) on the surface of macrophages were not affected by the co-culture of lamin-deficient cancer cells, suggesting that lamin knockdown in cancer cell might not influence macrophage activation." (PMID 40708945, 2025). "This increased percentage of CD14+CD80- can be explained by the polarization of macrophages to the M2 phenotype that highly expressed the CD163 receptors may be due to the secretion of adipocytes having myoCAF-like phenotype and cancer promoter microenvironment." (PMID 39072314, 2024). "Moreover, flow cytometric analysis showed significant increases in the percentage of CD206+, but not CD80+ macrophages, when they were stimulated with the CM from SA/Dox-treated cancer cells as compared to that of the macrophages stimulated with the CM from control cancer cells." (PMID 37696858, 2023). "It remains unclear whether a shift to pro-inflammatory states would similarly be observed within TAM populations from RMC tumors treated using immunotherapy targeting the classical PD-L1/2 or CD80/86 immune checkpoint regulators, which appear relatively absent in this cancer type." (PMID 35837094, 2022). "It was demonstrated that Bio‐MVs formulation with CD80 expression cells could control tumor growth because this kind of biomimetic nanoformulation can directly present the model antigen to cancer‐specific T cells without the need for professional antigen‐presenting cells (APC)." (PMID 34494387, 2021). "Furthermore, cancer cells directly evade immune surveillance and the antitumoral actions of natural killer cells by activating immunosuppressive mechanisms elicited by heterophilic complexes, joining cancer and immune cells, formed by PD-L1/PD1 and CD80/CTLA-4 plasma membrane proteins." (PMID 32555170, 2020). "Similarly, ligands for CTLA4 (CD86 and CD80) were almost never expressed in cancer cells." (PMID 31427603, 2019). "However, it has not been shown that such a treatment can induce CD80 expression in cancer cells." (PMID 23671644, 2013). "CD80 and CD86, while not as well characterized clinically, demonstrate similar immunosuppressive changes when expressed on cancer cells." (PMID 38542481, 2024). "Cancer cells also present the HLA class II antigen in the absence of the CD80/CD86 universe-stimulating molecules, this frequent representation of cancer cell antigens drives T-cell anergy thus, imparting cancer tolerance." (PMID 35517798, 2022). "As compared to autologous cells alone without MIM-SIS adjuvant, autologous cancer vaccines increased the expression of MHC-II and CD80 by 53.7% (MHC-II + CD80 + cells: 12.19 ± 3.70% vs. 7.93 ± 0.46%; p = 0.18)." (PMID 33208160, 2020). "When the immune homeostasis between the positive (TCR/MHC) and negative (CTLA-4/CD80, PD-1/PDL-1) signals for T cell activation is disrupted, cancer cells can evade the host’s immune response and escape from the attack of immune cells, thereby growing and proliferating uncontrollably." (PMID 41357573, 2025). "Interestingly, when macrophages were cocultured with radioresistant cells, both proinflammatory (CCR7, CD80) and anti-inflammatory markers (IL-10 and CCL18) were overexpressed, with no changes in cancer cell migration and invasion." (PMID 37347290, 2023). "It is understood that the binding of CD80 with CTLA-4, a receptor that acts as an important negative regulator of T-cell responses, is favorable for carcinogenesis because cancer cells commonly use the immunosuppressive function of regulatory T cells to avoid immunological attacks." (PMID 37765273, 2023).